TRDV2 (T cell receptor delta variable 2)
Description:
V region of the variable domain of T cell receptor (TR) delta chain that participates in the antigen recognition. Gamma-delta TRs recognize a variety of self and foreign non-peptide antigens frequently expressed at the epithelial boundaries between the host and external environment, including endogenous lipids presented by MH-like protein CD1D and phosphoantigens presented by butyrophilin-like molecule BTN3A1. Upon antigen recognition induces rapid, innate-like immune responses involved in pathogen clearance and tissue repair. Binding of gamma-delta TR complex to antigen triggers phosphorylation of immunoreceptor tyrosine-based activation motifs (ITAMs) in the CD3 chains by the LCK and FYN kinases, allowing the recruitment, phosphorylation, and activation of ZAP70 that facilitates phosphorylation of the scaffolding proteins LCP2 and LAT. This lead to the formation of a supramolecular signalosome that recruits the phospholipase PLCG1, resulting in calcium mobilization and ERK activation, ultimately leading to T cell expansion and differentiation into effector cells. Gamma-delta TRs are produced through somatic rearrangement of a limited repertoire of variable (V), diversity (D), and joining (J) genes. The potential diversity of gamma-delta TRs is conferred by the unique ability to rearrange (D) genes in tandem and to utilize all three reading frames. The combinatorial diversity is considerably increased by the sequence exonuclease trimming and random nucleotide (N) region additions which occur during the V-(D)-J rearrangements.
Synonyms: hDV102S1; MGC117421
Tractability: Antibody: UniProt places it where antibodies can reach, with high confidence; UniProt predicts a signal peptide or a membrane-spanning region; its Gene Ontology location is reachable by antibodies, with medium confidence.
Gene: T-cell receptor variable (V) gene on chromosome 14 (22,422,371 to 22,423,042, forward strand). Ensembl gene ENSG00000211821.
Subcellular location: Cell membrane
Gene Ontology:
Cellular component: plasma membrane
Homologues: Paralogues in human: IGLV1-50 (27% identical), IGLV1-51 (27% identical), IGLV8-61 (27% identical), IGKV2-28 (26% identical), IGKV2D-28 (26% identical), IGLV1-36 (26% identical), IGLV1-40 (26% identical), IGLV1-44 (26% identical), IGLV1-47 (26% identical), IGLV2-11 (26% identical), IGLV2-18 (26% identical), IGKV2-24 (25% identical), and 81 more.
Diseases named in the same sentence as TRDV2 in open-access papers:
TRDV2 is named in the same sentence as 5 diseases in open-access papers, as found by Europe PMC text mining. Sharing a sentence is not in itself a finding about the gene and the disease. The quoted sentences say what the papers report.
COVID-19 (1 paper, 2024). A disease caused by infection with severe acute respiratory syndrome coronavirus 2. "The expression of genes such as TRDV2, TRVD1, TRAV38-1, TRBV3-1, TRAV13-1, and TRBV2 was among the 15 most decreased in all data of severe COVID-19." (PMID 38262689, 2024).
leukemia (1 paper, 2021). A malignant (clonal) hematologic disorder, involving hematopoietic stem cells and characterized by the presence of primitive or atypical myeloid or lymphoid cells in the bone marrow and the blood. "Higher expression was linked to longer overall survival in AML, but only if leukemias were positive for TRDV2 expression." (PMID 35028614, 2021).
thymoma (1 paper, 2021). A neoplasm arising from the epithelial cells of the thymus. "Given the disproportionately high percentage of TRDV2+ AMLs and thymomas, we next assessed the prognostic association of transcripts encoding TCR subunits found in Vγ9Vδ2 cells, making comparisons with Vδ1 and αβ TCR subunits." (PMID 35028614, 2021). "A similar trend was seen in thymoma and also the remaining 20 tumors in which lower expression of TRDV2 was present." (PMID 35028614, 2021). "More important, we found significant positive associations between the γδ[T2] cell signature and both TRGV9 and TRDV2 in AML, but not thymoma." (PMID 35028614, 2021).
cancer (2 papers, 2021 to 2025). A tumor composed of atypical neoplastic, often pleomorphic cells that invade other tissues. "The abundant co-expression of TRDV2 and TGFB1 transcripts in AML suggests that a suitable environment may be present in this cancer to favor TGF-β conditioning of Vγ9Vδ2 T cells." (PMID 35028614, 2021). "Moreover, cytolytic activity (CYT) score, an index of cancer immunity that has been used for reflecting the status of antitumor immune response and as a prognostic marker, was found to be positively correlated with both TRGV9 and TRDV2 in CC tissue." (PMID 40091603, 2025).
TRDV2 also shares sentences with these, for which no sentence is quoted: thyroid cancer (1 paper).